APC (APC regulator of Wnt signaling pathway)
Diseases named in the same sentence as APC in open-access papers (continued):
Sharing a sentence is not in itself a finding about the gene and the disease.
gastric cancer (continued). "In gastric cancer, lncRNA LINC01133 is down-regulated in gastric cancer tissues and cell lines, and acts as competitive endogenous RNA (ceRNA) via sponging miR-106a-3p to regulate APC expression and Wnt/β-catenin pathway to inhibit gastric cancer progression and metastasis." (PMID 34888249, 2021). "miR-135b-5p modulates APC gene in both diffuse and intestinal gastric cancer subtypes." (PMID 33603784, 2021). "Thus, the gastric cancer organoids acquire WNT independently during tumor progression, e.g., by mutation of the adenomatous polyposis coli (APC) gene." (PMID 34488885, 2021). "Moreover, the cytoplasm lncRNA LINC01133 has been reported to act as a ceRNA for inhibiting gastric cancer progression by sponging miR-106a-3p to regulate APC expression and the Wnt/β-catenin pathway." (PMID 33465375, 2021). "Furthermore, microRNA-135, which regulates APC, has been reported to be upregulated by 1.6-fold in gastric cancers." (PMID 31248166, 2019). "Indeed, genetic mutations in components of this pathway such as APC, AXIN1/2 and CTNNB1 are well-established molecular events in colorectal, as well as gastric carcinomas and HCC." (PMID 22768190, 2012). "The proportion of pathogenic mutations in the examined WNT/APC/β-catenin pathway genes of the MSI-high subgroup of CDX2-induced, SOX2-suppressed gastric cancers was 28.6% (22 of 77 mutations), while the rest were of unknown significance, according to the evaluation in the OncoKB knowledgebase." (PMID 40149431, 2025). "For example, a high APC expression is an unfavorable prognostic factor for T4 gastric cancer and may be used as a novel biomarker for pathogenesis research, diagnosis, and the treatment of gastric cancer." (PMID 35938175, 2022). "These additional signals may also play a role in gastric carcinomas, given that WNT/APC/β-catenin pathway-activated mutations are not universally observed in CDX2-induced gastric cancers and are observed in lower frequency in the sub-set with SOX2-expression maintenance." (PMID 40149431, 2025). "In summary, EIF4A3-mediated circ_0008126 inhibited gastric cancer proliferation and metastasis in a miR-502-5p- and EIF4A3-dependent manner by attenuating the APC/β-catenin pathway, providing a potential target for the pathogenesis of GC and anti-cancer therapy." (PMID 39858034, 2025). "It was also verified that circ_0008126 inhibited gastric cancer proliferation and metastasis in a miR-502-5p and EIF4A3-dependent manner by attenuating the APC/β-catenin pathway, which extends our understanding of the dual regulatory pathway of circRNA." (PMID 39858034, 2025). "Some hypermethylated genes in prostate cancer are also hypermethylated in other types of cancer, such as p16 in colorectal cancer, gastric cancer, and leukemia; and CDH13, APC, and CDH1 in leukemia." (PMID 37234978, 2023). "For example, in gastric cancer, LINC01133 sponges miR-106-3p to upregulate APC expression and inhibit cancer progression." (PMID 35113786, 2022). "Major syndromes associated with GC are hereditary diffuse gastric cancer (HDGC; mutations in CDH1), gastric adenocarcinoma, proximal polyposis of the stomach (GAPPS; YYP1 binding motif of APC) and familial intestinal gastric cancer (FIGC)." (PMID 34576114, 2021).
gastric cancer (continued). "Methylation of genes such as RARB2, APC, CDKN2A, and RUNX3 has been shown to decrease following surgery in breast, esophageal, liver, and gastric cancers." (PMID 31615043, 2019). "Interestingly, potent anti-tumour effects of functional Dkk and/or sFRP are observed in gastric cancer cells with and without truncating mutations to APC, which provide compelling evidence that Wnt signalling can be further modulated in APC mutant gastric cancer cells." (PMID 29570681, 2018). "For gastric cancer methylated SOX17 and APC were independent predictors of survival, with an adjusted HR of 3.0 (95% CI 1.2–7.8) and 4.6 (95% CI 1.1–20.3) respectively." (PMID 30087854, 2018). "Moreover, well differentiated types of gastric cancers are found to originate from the intestinal metaplastic regions of the gastric mucosa and frequent loss of heterozygosity (LOH) can be seen on Chromosome 5, with APC gene located in the q arm of the chromosome." (PMID 28144288, 2017). "Another important factor is miR-135a, which binds to the APC gene, and inhibits STAT3-induced pro survival gene expression and induces apoptosis in gastric cancer and lymphoma." (PMID 26049416, 2015). "To further test the specificity of detecting methylated DNA in serum, we determined the methylation status of APC, E-cadherin, hMLH1 and TIMP3 in primary gastric cancer tissues by MSP." (PMID 15942635, 2005). "We thus find that alteration of the APC and MCC genes are infrequent in gastric cancers from the British population." (PMID 8855982, 1996). "Consistent with this, a potent anti-tumor effect was demonstrated by blocking FZD7 function in gastric cancer cells with and without mutant APC." (PMID 32486480, 2020). "In addition, NKX6.3 induced β-catenin binding to the β-catenin destruction complex, including GSK3β, Axin1, APC, and β-Trcp, in NKX6.3 stable gastric cancer cells." (PMID 27333045, 2016). "Further, in gastric cancer, as EBV-induced hypermethylation targets and silences key tumor suppressor genes including APC, RASSF1, BRCA1, THBS1, and CDKN2A, DNA methyltransferase inhibitors may also serve as a new therapeutic treatment for patients with EBV-positive gastric cancer." (PMID 37234978, 2023). "In contrast, a low expression level of APC (203525_s_at) was highly correlated with poor OS (P = 8.2e-16), FP (P = 9.2e-07) and PPS (P = 0.00023) for LUAD and poor RFS (P = 5.9e-08) for ovarian cancer and poor FP (P = 1.3e-06) and PPS (P = 1.6e-08) for gastric cancer." (PMID 35303016, 2022). "RASSF1A, p14ARF, and MGMT; CHRNA3, DOK1, and GNMT; p16, hMLH1, MINT1, MINT2, MINT12, MINT25, and MINT31; APC, CDH1, MHL1, CDKN2A, CDKN2B, and RUNX3; CDH1; DKK3; PTEN; MGMT; TFPI2; CACNA2D3; PCDH10; SOX2; MAL; and COX2 were previously reported to be hypermethylated in gastric cancer." (PMID 26121593, 2015).
polyposis (116 papers, 2005 to 2026). "We included individuals affected or at-risk for fCRC (Lynch syndrome, APC-associated polyposis, other risk-associated pathogenic variants and clinically defined fCRC)." (PMID 41203982, 2026). "The diagnosis was verified by endoscopic findings of polyposis and genetic analysis identifying a variant in the promotor 1B of the APC gene, NM_001127511.3: c.‐191T > C." (PMID 41523585, 2026). "The c.-190G>A (rs879253785) variant in the 1B promoter of the APC gene, which was detected in two unrelated patients with polyposis, is located at a distance of 47,363 bp from the first coding nucleotide of the gene, located in the second exon." (PMID 41170447, 2025). "Most pathogenic variants in APC affect Wnt signaling by promoting β-catenin accumulation, leading to polyposis." (PMID 40237877, 2025). "The specific APC mutation (c.3927_3931delAAAGA) falls within the mutation cluster region associated with severe polyposis and early cancer development, validating the genotype-phenotype correlation." (PMID 40706335, 2025). "Accordingly, detection of a CTNNB1 mutation supports a sporadic origin, whereas an APC germline alteration and/or a polyposis phenotype suggests a hereditary form." (PMID 41227209, 2025). "Subsequent genetic testing confirmed a pathogenic variant in the APC gene, and colonoscopy revealed extensive polyposis." (PMID 40416288, 2025). "In a large cohort of 8676 individuals with polyposis, 24% of them had a pathogenic APC or MUTYH alteration." (PMID 40095498, 2025). "In our cohort, some patients presented with polyposis on colonoscopy but had VUS or benign APC variants." (PMID 39227904, 2024). "Mutations located in the proximal portion of the APC protein (before codon 1,249) are associated with fewer than 1,000 polyps (sparse polyposis) whereas mutations between codons 1,250 and 1,330 are associated with more than 5,000 polyps (profuse polyposis)." (PMID 38555871, 2024). "We found the p.Q82* mutation in the homozygous state in three polyposis patients, and in one with the detected APC mutation, it was heterozygous." (PMID 37834005, 2023). "Prior studies reported that rapamycin prevents APC-deficiency induced polyposis in several mouse models by inhibiting translation-related targets such as mTORC1, S6 and eEF2." (PMID 37138032, 2023). "This includes LS, APC-associated polyposis, Peutz–Jeghers Syndrome (PJS), Juvenile Polyposis Syndrome (JPS) and MUTYH-associated polyposis." (PMID 37258796, 2023). "All these facts make the p.Q82* of the NTHL1 gene screening reasonable in polyposis patients (especially in an unusual disease course), with APC, MUTYH, STK11, BMPR1A, and SMAD4 mutations excluded." (PMID 37834005, 2023). "Regardless of the mechanism by which Wnt is upregulated in FGPs in patients with FAP, the same underlying APC mutation appears to have strikingly different effects in driving polyposis in the human gastric corpus versus antrum." (PMID 37943618, 2023). "Mosaicism in CRC susceptibility genes, mainly APC, has been reported in a significant portion of patients with undiagnosed polyposis." (PMID 35158896, 2022). "Although less common and less likely to dramatically increase FAP risk than APC mutations, inherited mutations in many other genes can also lead to polyposis and CRC." (PMID 36553592, 2022). "Polyposis caused by pathogenic germline variants in the APC gene is sometimes referred to as APC-associated polyposis." (PMID 34185173, 2021). "APC is a good example of this, where variants in the “mutation cluster region” including codon 1309 produce profuse polyposis, but variants at the 3′ and 5′ end of the gene are associated with attenuated polyposis." (PMID 34680910, 2021). "A recent study was focused on the effects of daily oral administration of high-fructose corn syrup (HFCS) in adenomatous polyposis coli (APC) mutant mice, which are predisposed to develop intestinal tumors." (PMID 34052986, 2021).
polyposis (continued). "Meanwhile, gastric cancers that develop in GAPPS, which is a polyposis limited to the stomach due to pathogenic germline variants in the promoter 1B of the APC gene, require differentiation at the time of initial diagnosis due to its high malignancy." (PMID 34185173, 2021). "The management of polyposis patients, who are carriers of APC mutations, requires a colonoscopy every one to two years, from the age of 10–12 years." (PMID 33923292, 2021). "We have previously reported tentative evidence that polymorphisms in CD36 influence the age at which polyposis expression occurs, based on a relatively small population of patients with confirmed APC pathogenic variants." (PMID 33926505, 2021). "The observation of an increased rate of C:G > A:T transversions in APC in tumors led to the discovery of MUTYH-associated polyposis in the early 2000s." (PMID 33228212, 2020). "Subsequently, germline pathogenic variants in APC, located in this 5q21 locus, were identified as the cause of the polyposis phenotype." (PMID 33228212, 2020). "The genotype impact on phenotype is studied by many research groups, leading to the correlation of mutated codons with a clinical phenotype of APC-associated polyposis conditions." (PMID 31547110, 2019). "In this case, the phenotype is considered to be associated with APC-associated polyposis conditions." (PMID 31547110, 2019). "We had also earlier reported that spontaneous polyposis in genetically susceptible APC deficient mice is marked by mixed TH2 and TH17 inflammation, and that MCs and GATA3 positive cells tend to accumulate together inside polyps." (PMID 31849960, 2019). "Two APC truncating mutations were detected in two subjects diagnosed with late-onset full-blown polyposis and a family history initially suspicious of recessive inheritance." (PMID 31285513, 2019). "In the model of TS4/APC specifically, our mouse group reported a decreased F/B ratio in association with worsening polyposis." (PMID 29462896, 2018). "The mutation in this patient affected codon 1450, a site of the APC gene associated with classical polyposis and desmoid development." (PMID 29368261, 2018). "In an APC-based mouse model of polyposis, an increase in the F/B ratio was associated with a decrease in tumor load." (PMID 29462896, 2018). "It has been reported that the location of the germline mutations in the APC gene determines the severity of polyposis." (PMID 30256815, 2018). "The Wnt-driven ApcMin/+ mouse model quickly recapitulates both genetic, as well as inflammatory processes of human sporadic intestinal tumorigenesis by exhibiting polyposis following loss of APC within 16 to 20 weeks of age." (PMID 28881611, 2017). "APC is the only gene in which pathogenic variants cause APC-associated polyposis conditions, while CTNNB1 gene mutations characterize the sporadic DTs in around 85% of the cases." (PMID 28418912, 2017). "The severity of polyposis, reflected by the number of colorectal adenomas and the age of onset, is correlated with the site of the APC mutation." (PMID 26880076, 2016). "The frequency of detectable APC mutations in polyposis patients varies a lot depending on the method of ascertainment of the patients and families, and the strategies used for mutation screening." (PMID 27683109, 2016). "There were only a few, but definitive dissimilarities between APC- and MUTYH-associated FAP in our cohort: the age at onset of polyposis was significantly delayed for biallelic MUTYH mutation carriers as compared to patients with an APC mutation." (PMID 26446593, 2016). "Patients with APC mutations between codons 1249 and 1549 develop polyposis at an early age and exhibit worse survival prognosis while patients with APC mutations in codons 312 to 412 have a later onset of polyposis and exhibit improved survival rates." (PMID 27000756, 2016). "Approximately 8–12% of individuals with an APC-associated polyposis condition and >100 polyps have a partial or whole APC gene deletion." (PMID 26311738, 2015).
polyposis (continued). "In this sense, a recent study demonstrated that up to 8% of APC/MUTYH-negative polyposis patients presented a deep intronic APC variant that led to an aberrant transcript." (PMID 23561487, 2013). "The mutation c.447dupC (p.Lys150GlnfsX18), identified in family ID05, is located in exon 4; the 5′ region of the APC gene is generally associated with attenuated polyposis and later age of onset." (PMID 23561487, 2013). "Recently, Nieuwenhuis and Vasen (2007) performed a meta-analysis and proposed categorization of the phenotypes into three degrees of polyposis severity and the associated site of APC mutation." (PMID 23561487, 2013). "Nine (64%) of 14 FAP families with an APC pathogenic mutation presented the expected polyposis severity according to the location of the APC mutation, while the remaining five families exhibited discordant results from the anticipated phenotype." (PMID 23561487, 2013). "Our data contradict those obtained in the mouse showing that polyposis can initiate after a complete loss of both APC alleles." (PMID 22509309, 2012). "Currently, these tumours are regarded as a clonal proliferation of myofibroblasts that show APC (adenomatous polyposis coli) gene mutations." (PMID 22933936, 2011). "Usually, affected individuals acquire a defective copy of the APC gene from the affected parent, with a somatic mutation of the other copy of the gene causing the initiation of polyposis." (PMID 19424478, 2008). "Mutations between APC codons 1250 and 1464 cause profuse polyposis, generally with > 5000 polyps, and the recurrent codon 1309 mutation is associated with early onset and development of thousands of polyps." (PMID 19036155, 2008). "In these patients, polyposis arises from multiple somatic mutations that accumulate in the APC gene due to the biallelic inactivation of the MYH." (PMID 15833136, 2005). "However, not all patients meeting clinical criteria for FAP carry pathogenic APC mutations, as there is genetic heterogeneity responsible for FAP with the polyposis explained by genetic and environmental factors other than pathogenic APC mutations." (PMID 39227904, 2024). "We speculate that heterozygous loss of APC confers genetic instability that could sensitize the tissue to polyposis in lieu of a second-hit APC mutation." (PMID 37943618, 2023). "Therefore, the substantial deletion of the APC gene in this family is the causative mutation for polyposis." (PMID 37577746, 2023). "Both had been previously tested for MUTYH but not for APC, probably due to the lack of family information at the time of diagnosis, the late polyposis onset of the probands, and also the stricter clinical criteria for the recommendation of full APC mutational screening for AAP in our hospital." (PMID 31285513, 2019). "The severity of polyposis is correlated with the site of the APC mutation." (PMID 26880076, 2016). "However, there is also phenotypic variability within families with the same underlying APC mutation, suggesting that additional factors influence the severity of polyposis." (PMID 26880076, 2016). "However, there is also phenotypic variability within FAP families with the same underlying gene defect, suggesting that beside the APC genotype, other factors also play a role in determining the severity of polyposis and the risk of CRC." (PMID 26880076, 2016). "In spite of several evidences that showed as different phenotypes can be classified based on degree of severity of polyposis and site of APC gene mutation, there is a scarcity of data concerning correlations between disease manifestations and APC germline reduced expression." (PMID 26511139, 2015). "An APC-associated polyposis condition should be suspected if any of the following criteria is present: at least 10–20 cumulative colorectal adenomatous polyps, a family history of multiple colorectal polyps, and having a known APC variant and/or typical extracolonic features." (PMID 37239385, 2023).